IL5 (interleukin 5)
Diseases named in the same sentence as IL5 in open-access papers (continued):
Sharing a sentence is not in itself a finding about the gene and the disease.
asthma (continued). "In addition, we observed that the P+S coculture significantly reduced IL-5 levels in all of the children with asthma who had mild, moderate, severe, or extremely severe asthma symptom scores." (PMID 31673233, 2019). "In asthma patients, the Th2-related cytokines such as IL-4, IL-5, and IL-13 are usually increased." (PMID 31790411, 2019). "In regards to T lymphocytes, Th2 cells are considered one of the central players in asthma pathogenesis, as long as these cells participate in and coordinate the onset and progression of the inflammatory response in asthma through the release of cytokines, especially IL-4, IL-5, IL-9, and IL-13." (PMID 31019244, 2019). "Another very recent study, enrolling 1016 infants <12 months in 17 U.S. centers, confirms that high levels of cytokines inducing a Th2 immune response (IL-4, IL-5, IL-13, and Thymic Stromal Linphopoyetin) are significantly related to the onset of asthma in infants up to four years of age." (PMID 31195744, 2019). "Furthermore, in comparison to both healthy controls and subjects with mild asthma, higher serum IL-5 concentrations were detected in patients with severe disease." (PMID 31920718, 2019). "The anti-IL-5 antibody now is an add-on controller for patients with severe asthma." (PMID 31284537, 2019). "Furthermore, increased numbers of IL-5+ and IL-13+ ILC2s were found in sputum after allergen challenge in asthma patients." (PMID 31443563, 2019). "Upstream regulator predictions suggested that six inflammatory cytokines were upregulated and one downregulated (Z-Score > 1 or <−1); among the upregulated cytokines, the classical Th2 cytokines interleukin (IL)-4 and IL-5 drive M2 macrophage polarization in asthma pathogenesis." (PMID 31133848, 2019). "However, in 2009, two small but well-designed randomized controlled trials were contracted that meant to change the road of anti-IL-5 treatment in asthma." (PMID 31480806, 2019). "Asthma is an eosinophilic/Th2 disorder, and novel therapeutics targeting Th2 cytokines (IL-4, IL-5 and IL-13) and IgE have achieved excellent improvements in disease control, although these therapeutics are applicable to only a sub group of patients in clinical studies." (PMID 31692453, 2019). "In other AAD models, specifically in murine asthma, airway goblet cell hyperplasia was found to be directly induced by Th2-derived IL-9, whereas IL-4, IL-5, and IL-13 independently induce goblet cell hyperplasia, though indirectly via neutrophilic granulocytes." (PMID 30845208, 2019). "In an in vitro study, psoralen significantly suppressed T helper type 2 (Th2) cytokines such as IL-4, IL-5 and IL-13 and therefore regarded as a critical component of PF for its in vivo therapeutic effects on airway hyperresponsiveness and inflammation of asthma." (PMID 31827595, 2019). "Type 2‐targeting biologics such as anti‐IgE, anti‐IL4Rα, anti‐IL5, and anti‐IL5Rα have entered the market for selected pheno/endotypes of asthma patients and may soon also become available for CRSwNP patients." (PMID 31090937, 2019). "Th2 cytokines such as IL-4, IL-5, IL-13, and IL-9 also have the same effects on asthma." (PMID 31143692, 2019). "Antagonists to IL-5 have been produced for the treatment of severe asthma." (PMID 32010048, 2019). "Interestingly, although IL‐27 production was increased in the IfitmF–/– mice compared to WT in our asthma experiments, levels of Il4, IL‐5, IL‐13, IL‐6, IL‐10, IL17, and TNF‐α were all decreased." (PMID 30365177, 2019). "These genes have been demonstrated to influence a number of key components of asthma pathology, including eosinophil and T cell migration, production of Th2 cytokines (IL-4, IL-5, and IL-13), mast cell degranulation, IgE production, and airway hyperresponsiveness." (PMID 31221987, 2019).
asthma (continued). "Furthermore, chronic exposure of the lungs of OVA/ALUM-vaccinated mice to OVA, as a model of asthma, led to an increase in IL-5 levels and number of eosinophils in the resulting bronchoalveolar lavage fluid of those mice." (PMID 31392268, 2019). "Benralizumab, a humanized, anti-interleukin-5 (anti-IL-5) receptor α monoclonal antibody that directly and rapidly depletes eosinophils, has shown significant efficacy in reducing asthma exacerbations and improving lung function in moderate to severe eosinophilic asthma patients." (PMID 31145343, 2019). "Interestingly, the present study assessed patients whose asthma was unresponsive to a biologic treatment targeting the IgE pathway and who were switched to an alternative treatment targeting the IL‐5 pathway." (PMID 31049972, 2019). "Indeed, high levels of IL-5 and eotaxins were found in induced sputum from patients experiencing acute asthma exacerbations." (PMID 31920718, 2019). "IL-5 was also down-regulated in horses with mild asthma (2.17-fold, p = 0.048)." (PMID 31694631, 2019). "IL-5 promotes chronic, inflammatory asthma, and 4μ8c blocks its expression in T cells in vitro." (PMID 30630412, 2019). "Administered in remission phase, the effects of YPFS against asthma recurrence was determined by significantly reduced airway resistance, IgE level in serum, IL-5 and IL-13 production, peripheral eosinophils, and total cells in BALF, as well as remarkably alleviated pulmonary inflammation." (PMID 32076408, 2019). "Recently, a cluster analysis of patients with chronic rhinosinusitis with nasal polyp (CRSwNP) reported that both IL-5-positive clustering and SE-IgE-positive clustering were important factors for eosinophilic inflammation when asthma was included in the analysis as a comorbidity." (PMID 31606052, 2019). "Therefore, the asthma profile that shows elevated IL-4, IL-5, and IL-13, characteristic of severe asthma in children, cannot be readily ascribed to adults." (PMID 31336954, 2019). "IL-4, IL-5, and IL-13 belong to Th2 cytokines, which play a fundamental effect in asthma." (PMID 30834081, 2019). "IL-5 also inhibits eosinophil apoptosis, and sputum IL-5 levels were reported to be negatively correlated with apoptotic eosinophils in subjects with either asthma exacerbations or stable disease." (PMID 31920718, 2019). "Notably, in the culture, MSCs at different concentrations exhibited the ability to suppress IL-5 in children with asthma." (PMID 31673233, 2019). "The story of anti-IL-5 treatment in asthma is definitely a fascinating one." (PMID 31480806, 2019). "Mepolizumab, an anti-interleukin (IL)-5 therapy, was approved in 2015 for add-on maintenance treatment of patients with severe asthma ≥ 12 years of age and with an eosinophilic phenotype; in 2018 the EU license was extended to include patients with severe asthma ≥ 6 years of age." (PMID 31507641, 2019). "IL-5 levels were also decreased in children with all severities of asthma (P < 0.05)." (PMID 31673233, 2019). "In Der p 2 stimulation, substantial IL-5 and IL-13 levels were detected in most patients with asthma but not in healthy controls; IL-5 production was detectable in all patents with asthma, and IL-13 was detectable in 10 of the 12 patients with asthma." (PMID 31861989, 2019). "Biologic therapies targeting immunoglobulin E or interleukin-5 are recent additions to the asthma treatment armamentarium and may be useful in select cases of difficult to control asthma." (PMID 30275843, 2018). "Furthermore, ovalbumin-induced pulmonary inflammation is strongly inhibited by genetic depletion of plasminogen via suppressing the downregulation of IL-5, tumour necrosis factor-α and gelatinases, which are mediators of asthma and collagen deposition." (PMID 30089611, 2018).
asthma (continued). "Although allergic asthma has always been considered to be a Th2 disease with increased eosinophils and Th2 cytokines such as IL-4, IL-5 and IL-13, severe asthma related to clinical resistance may result from a mixed Th2/Th17 response." (PMID 29540228, 2018). "For patients with severe uncontrolled asthma, four monoclonal antibodies (mAbs) against immunoglobulin E (IgE) or interleukin (IL)-5 are available for clinical use by either subcutaneous (SC) or intravenous (IV) administration as an add-on to ICS plus LABA therapy." (PMID 30115042, 2018). "Elevation of IL-4, IL-5, IL-9, and IL-13 was noted in asthma cytokine alterations." (PMID 30423980, 2018). "A recent meta-analysis of 20 studies involving 7,100 asthma patients found anti-IL-5 therapies with different mode of actions could provide clinical benefit for patients with severe, eosinophilic asthma." (PMID 29696083, 2018). "In summary, serum IL-4, IL-5 and IL-10, adhesion molecules, and sE-selectin were all involved in the pathogenesis of allergic rhinitis and asthma, which can be used to diagnose the degree of respiratory allergic diseases, thus being potentially applicable to clinical practice." (PMID 30344593, 2018). "The type 2 cytokines such as IL-4, IL-5, and IL-13 are key players in the pathogenesis of asthma." (PMID 29593738, 2018). "The mRNA expression levels of IL-5 were correlated with the clinical severity of asthma." (PMID 29991953, 2018). "Indeed, CRSwNP disease can be further classified on the basis of distinct biomarkers (IgE, SE-IgE, and IL-5) that are increased in nasal polyps tissue when there is comorbidity (asthma)." (PMID 29784985, 2018). "Nasal polyps in severe asthma are predominantly eosinophilic, and treatment with anti-IL5 may be a future treatment option." (PMID 29535852, 2018). "The present review will examine recent findings and outline how these findings may be applied to the development of a vaccine against asthma targeting IL-5." (PMID 30405579, 2018). "Analyzing the efficacy studies of the three Anti-IL5 mAbs, it is important to focus on the primary outcome, which is, for mepolizumab and benralizumab, the reduction in annual asthma exacerbation numbers and, limited to reslizumab, the improvement in lung function test." (PMID 30498762, 2018). "In experimental asthma models and clinical studies of asthmatic populations, increases in pro-inflammatory cytokines, such as IL-4 and IL-5, are directly related to the differentiation, proliferation, recruitment, and survival of inflammatory cells in allergic inflammation." (PMID 30135462, 2018). "However, the ability of IL-4-, IL-5-, or IL-13-producing Treg cells in the development of asthma needs to be further investigated." (PMID 30013989, 2018). "The US FDA has approved drugs for asthma (anti-IL-5 agents, including mepolizumab, reslizumab, benralizumab, and anti-IgE omalizumab); atopic dermatitis (anti-IL-4/IL-13 agent dupilumab), psoriasis (anti-IL-17 secukinumab and brodalumab), and chronic urticaria (anti-IgE and omalizumab)." (PMID 29707206, 2018). "Compared with the control group, the relative expression levels of miR-1 and IFN-γ in the peripheral blood of children with asthma in the study group were significantly decreased, whereas the expression levels of IL-4, IL-5, IL-8, and TNF-α were significantly increased." (PMID 30046607, 2018). "Our study suggests that up to 41% of patients with severe asthma could qualify for new anti-IL-5 and anti-IL-5 receptor α therapies based on a single blood eosinophil count." (PMID 29713354, 2018). "To further clarify whether the WTD can adjust the apoptosis state of EOS to achieve the purpose of alleviating asthma, we use ELISA method to detect IL-5, IL-10, CSF, CCL5, TGF-β, and IFN-γ in rat serum." (PMID 29713367, 2018).
asthma (continued). "Moreover, eosinophils obtained from the bronchial lavage of atopic asthmatics show increased expression of IL-5 mRNA following allergen challenge and there is a correlation between the IL-5 concentration in the serum and severity of asthma." (PMID 30013547, 2018). "LAMAs or biologic therapies targeting IgE or IL-5 may be useful in select cases of difficult to control asthma." (PMID 30275843, 2018). "Furthermore, the knowledge of eosinophils involvement in asthma and the potential to block IL-5 stimulated other research studies to better identify the field of application of the new anti-IL5 mAbs." (PMID 30498762, 2018). "To date, IL-5 and IgE were identified as indicators for patients with CRSwNP and additional asthma." (PMID 29564208, 2018). "Furthermore, in severe asthmatic patients with sustained blood or sputum eosinophilia, anti-IL-5 treatment decreases both blood eosinophil counts and asthma exacerbation frequency." (PMID 30323811, 2018). "Other clinical endpoints, in addition to annual exacerbation rate, as the need of frequent oral corticosteroid use, asthmatic symptoms and quality of life, should be taken into account by clinicians who consider anti-IL-5 therapy for their patients with severe asthma." (PMID 30498762, 2018). "In addition, it would be of interest to investigate other classical targets in asthma disease and to compare the effects of NS preparations on the release of Th2 cytokines IL-4, IL-5, and IL-13 in in vitro models." (PMID 30333747, 2018). "Anti-IL-5 mAbs have been unable to completely abolish both blood and airway eosinophils in asthma patients; these data could be explained by cytokines others than IL-5, such as IL-3, GM-CSF, and IL-9, sustaining the eosinophilic airway inflammation." (PMID 29879991, 2018). "The role of IL-5 in asthma, especially in asthma with acute exacerbation has been demonstrated." (PMID 30210646, 2018). "As expected, eosinophils and IL-5 levels were significantly elevated in patients with asthma." (PMID 30005648, 2018). "Group 2 innate lymphoid cells (ILC2s) are a relatively newly discovered lymphocyte population that promotes features of allergic airway diseases including asthma and chronic rhinosinusitis through secretion of the type 2 cytokines IL-4, IL-5 and IL-13 among others." (PMID 28959799, 2017). "Using a mouse model of ovalbumin-induced asthma, we showed that p75NTR expression by pDCs was essential for mediating allergic inflammation characterized by increased IL-4, IL-5, and IL-13 secretion; eosinophilia; lung tissue inflammation; and Goblet cell hyperplasia." (PMID 28516419, 2017). "IL-4, IL-5, and IL-13 are essential Th2 cytokines in driving the development of asthma." (PMID 28106744, 2017). "Historically, IL-5 has been considered pro-inflammatory in allergic diseases including asthma." (PMID 29163523, 2017). "However, none of the trials that have been undertaken to assess the efficacy of blocking IL-5 in severe asthma have assessed efficacy in children alone." (PMID 28725641, 2017). "IL-5 and IL-13 are important cytokines in the asthma by recruiting eosinophil and neutrophil." (PMID 28423665, 2017). "In addition, in OME patients with asthma, there was a significant correlation between the percentage of eosinophils and IL-5 levels in MEE." (PMID 29158869, 2017). "IL-5 is highly specific for eosinophilic inflammation and may play an important role in eosinophil survival, maturation, and activation in asthma." (PMID 28570692, 2017). "Our results may indicate that suppression of either IL‐5 or IL‐4/IL13 is insufficient and it is necessary to suppress both Type‐2 cytokines such as IL‐5 and IL‐4/IL‐13 for the improvement of asthma control." (PMID 28474411, 2017). "Notably, treatment with a DNA enzyme that cleaved GATA3 mRNA resulted in reduced airway eosinophilia and plasma levels of IL-5 in individuals with asthma, highlighting the feasibility of targeting TFs in patients with eosinophil disorders." (PMID 28791289, 2017).
asthma (continued). "Thus, IL-33 production induces IL-5 and IL-13 release in asthma, cytokines that are produced by Th2 and ILC2 cells." (PMID 28262704, 2017). "Recently, ILC2s were found in the bronchoalvoelar lavage (BAL) and sputum of patients with asthma, and the proportion of IL-5+IL-13+ ILC2s in the sputum of patients with severe asthma was higher than that in corresponding samples from patients with mild asthma." (PMID 28271447, 2017). "The superior suppression of asthma-like phenotype by CAR Treg treatment in relation to wt Treg injection was again demonstrated by significant reduction of antigen-specific IL-5 levels in cell culture supernatants of lung cells and splenocytes after in vitro restimulation with OVA." (PMID 28955341, 2017). "In a mouse model of house dust mite-induced asthma in which AMs are depleted using clodronate liposomes, Th2 cytokines, such as IL-4, IL-5, and IL-13, and inflammatory cytokines and eosinophil recruitment were increased in BAL fluid, suggesting an immunosuppressive role of AMs." (PMID 28751894, 2017). "However, targeting eosinophilic inflammation using a monoclonal antibody to interleukin (IL)-5 has shown a significant reduction in exacerbations in adults with severe asthma." (PMID 28725641, 2017). "Furthermore, those asthma patients with higher levels of nasal IL-5 and IL-13 prior to RV infection, tended to be those with higher nasal levels of IL-5 and IL-13 after infection." (PMID 28373098, 2017). "Biologicals targeting the Th2-eosinophil nexus such as anti–interleukin (IL)-4, anti–IL-5, and anti–IL-13 are ineffective in asthma as a whole but are more effective if patients are selected using cellular (eg, eosinophils) or molecular (eg, periostin) biomarkers." (PMID 26334389, 2016). "In mice, it could be shown that the expression of TSLP, IL4, IL5 and IL13 induces atopic dermatitis as well as asthma, and IL5 knockout mice exposed to allergens are less prone than wild-type to develop skin eosinophilia and epidermal thickening." (PMID 27431613, 2016). "A reasonable question is whether in a newly encountered case of severe asthma anti-IgE or anti-IL-5 should be the first choice." (PMID 27834175, 2016). "However, there are two very important issues when evaluating the results of the initial anti-IL-5 studies that yielded disappointing results on asthma outcomes." (PMID 27834175, 2016). "The normal control group had significantly lower IL-5 levels compared with the asthma (p < 0.001) and TSA groups (p = 0.039); whereas, the asthma group had significantly higher IL-5 levels compared with the DXA, PCI-34051, and givinostat groups (all p ≤ 0.014)." (PMID 27565183, 2016). "This may have implications for monitoring the cardiovascular safety of anti-IL-5 therapy for asthma, and for the interpretation of these tests in clinical practice." (PMID 27621833, 2016). "In addition, asthma therapy with new biologicals, for example anti–IL-5 or anti–IL-13, appears to be far more effective if patients are selected using cellular (eg, eosinophils) or molecular (eg, periostin) biomarkers." (PMID 26334389, 2016). "Here, we conducted a meta-analysis of randomized, controlled trials (RCTs) to assess whether anti-IL-5 monoclonal antibodies therapy is safe and effective in patients (more than 12 years) with asthma." (PMID 27875559, 2016). "In addition, the relative contribution of IL-5 and IL-13 production by ILC2s in human asthma in comparison to Th2 cells, other innate cells and structural cells, like epithelial cells, needs to be further elucidated." (PMID 26965110, 2016). "Asthma is typically thought to be marked by a shift towards Th2-dependent processes, both an early-phase response involving IL-4 and IL-13 and a late-phase response involving IL-5." (PMID 27965775, 2016). "The importance of IL-5 in asthma pathobiology has been elucidated by studies on anti-IL-5." (PMID 27834175, 2016).